GLRA1 (glycine receptor alpha 1)
Description:
Subunit of heteromeric glycine-gated chloride channels. Plays an important role in the down-regulation of neuronal excitability. Contributes to the generation of inhibitory postsynaptic currents. Channel activity is potentiated by ethanol. Potentiation of channel activity by intoxicating levels of ethanol contribute to the sedative effects of ethanol (By similarity).
Synonyms: HKPX1; STHE
Tractability: Small molecule: an approved drug acts on it; a structure with a bound ligand is known; a high-quality ligand is known; it belongs to a druggable protein family. Antibody: UniProt places it where antibodies can reach, with high confidence; its Gene Ontology location is reachable by antibodies, with high confidence; UniProt predicts a signal peptide or a membrane-spanning region. PROTAC: a small molecule that binds it is known.
Target class: Ion channel; Ligand-gated ion channel; Glycine receptor
Gene: Protein-coding gene on chromosome 5 (151,822,513 to 151,924,851, reverse strand). Ensembl gene ENSG00000145888.
Subcellular location: Postsynaptic cell membrane; Synapse; Perikaryon; Cell projection, dendrite; Cell membrane
Subcellular location (Human Protein Atlas): Plasma membrane; Vesicles
Pathways (Reactome):
Neuronal System: Neurotransmitter receptors and postsynaptic signal transmission
Gene Ontology:
Molecular function: extracellularly glycine-gated chloride channel activity; glycine binding; ligand-gated monoatomic ion channel activity involved in regulation of presynaptic membrane potential; protein binding; taurine binding; zinc ion binding; excitatory extracellular ligand-gated monoatomic ion channel activity; extracellular ligand-gated monoatomic ion channel activity; monoatomic ion channel activity; transmembrane signaling receptor activity; transmitter-gated monoatomic ion channel activity; transmitter-gated monoatomic ion channel activity involved in regulation of postsynaptic membrane potential
Biological process: cellular response to amino acid stimulus; cellular response to ethanol; cellular response to zinc ion; chloride transmembrane transport; chloride transport; monoatomic ion transport; muscle contraction; negative regulation of transmission of nerve impulse; neuropeptide signaling pathway; positive regulation of acrosome reaction; regulation of membrane potential; startle response; inhibitory postsynaptic potential; response to alcohol; synaptic transmission, glycinergic; excitatory postsynaptic potential; monoatomic ion transmembrane transport; regulation of presynaptic membrane potential
Cellular component: glycine-gated chloride channel complex; intracellular membrane-bounded organelle; plasma membrane; glycinergic synapse; membrane; neuron projection; neuronal cell body; perikaryon; postsynaptic membrane; synapse; dendrite; external side of plasma membrane; inhibitory synapse
Genetic constraint (gnomAD): Loss-of-function variants: 28 observed, 39.38 expected, observed/expected ratio (o/e) 0.71, 90% interval 0.53 to 0.98. The upper end of that interval is the gene's LOEUF score, 0.98, which puts it in group 4 of 6, group 1 being the genes least tolerant of losing a copy. Missense variants: 361 observed, 510.37 expected, observed/expected ratio (o/e) 0.71, 90% interval 0.65 to 0.77. Synonymous variants: 167 observed, 192.84 expected, observed/expected ratio (o/e) 0.87, 90% interval 0.76 to 0.99.
Homologues: Orthologues: dog GLRA1 (99% identical), macaque GLRA1 (99% identical), rabbit GLRA1 (99% identical), mouse Glra1 (99% identical), pig GLRA1 (99% identical), guinea pig GLRA1 (99% identical), chimpanzee GLRA1 (96% identical), rat Glra1 (95% identical), tropical clawed frog glra1 (87% identical), zebrafish glra1 (86% identical). Paralogues in human: GLRA3 (82% identical), GLRA2 (76% identical), GLRB (48% identical), GABRB3 (38% identical), GABRB2 (37% identical), GABRA2 (36% identical), GABRB1 (36% identical), GABRA4 (35% identical), GABRR2 (35% identical), GABRD (35% identical), GABRA3 (34% identical), GABRG1 (34% identical), and 33 more.